LAMP2 (lysosome associated membrane protein 2)
Description:
Lysosomal membrane glycoprotein which plays an important role in lysosome biogenesis, lysosomal pH regulation and autophagy. Acts as an important regulator of lysosomal lumen pH regulation by acting as a direct inhibitor of the proton channel TMEM175, facilitating lysosomal acidification for optimal hydrolase activity. Plays an important role in chaperone-mediated autophagy, a process that mediates lysosomal degradation of proteins in response to various stresses and as part of the normal turnover of proteins with a long biological half-live. Functions by binding target proteins, such as GAPDH, GPX4, NLRP3 and MLLT11, and targeting them for lysosomal degradation. In the chaperone-mediated autophagy, acts downstream of chaperones, such as HSPA8/HSC70, which recognize and bind substrate proteins and mediate their recruitment to lysosomes, where target proteins bind LAMP2. Plays a role in lysosomal protein degradation in response to starvation (By similarity). Required for the fusion of autophagosomes with lysosomes during autophagy. Cells that lack LAMP2 express normal levels of VAMP8, but fail to accumulate STX17 on autophagosomes, which is the most likely explanation for the lack of fusion between autophagosomes and lysosomes. Required for normal degradation of the contents of autophagosomes. Required for efficient MHC class II-mediated presentation of exogenous antigens via its function in lysosomal protein degradation; antigenic peptides generated by proteases in the endosomal/lysosomal compartment are captured by nascent MHC II subunits. Is not required for efficient MHC class II-mediated presentation of endogenous antigens. [Isoform LAMP-2C]: Modulates chaperone-mediated autophagy. Decreases presentation of endogenous antigens by MHCII. Does not play a role in the presentation of exogenous and membrane-derived antigens by MHCII. (Microbial infection) Supports the FURIN-mediated cleavage of mumps virus fusion protein F by interacting with both FURIN and the unprocessed form but not the processed form of the viral protein F.
Synonyms: LAMP-2; CD107b; DND; LAMPB; LGP-96; LGP110
Tractability: Antibody: UniProt places it where antibodies can reach, with high confidence; its Gene Ontology location is reachable by antibodies, with high confidence; UniProt predicts a signal peptide or a membrane-spanning region. PROTAC: its protein half-life has been measured.
Gene: Protein-coding gene on chromosome X (120,426,148 to 120,469,365, reverse strand). Ensembl gene ENSG00000005893.
Subcellular location: Lysosome membrane; Endosome membrane; Cell membrane; Cytoplasmic vesicle, autophagosome membrane
Subcellular location (Human Protein Atlas): Endoplasmic reticulum; Plasma membrane; Vesicles
Pathways (Reactome):
Autophagy: Chaperone Mediated Autophagy
Hemostasis: Platelet degranulation
Immune System: Neutrophil degranulation
Gene Ontology:
Molecular function: enzyme binding; ion channel inhibitor activity; protein binding; protein-macromolecule adaptor activity; protein domain specific binding
Biological process: chaperone-mediated autophagy; lysosomal lumen acidification; lysosomal protein catabolic process; positive regulation of ferroptosis; protein targeting to lysosome involved in chaperone-mediated autophagy; regulation of protein stability; autophagosome maturation; cellular response to starvation; protein import; protein stabilization; protein targeting; autophagy
Cellular component: autolysosome; endosome membrane; extracellular exosome; extracellular region; late endosome; late endosome membrane; lysosomal membrane; lysosome; membrane; plasma membrane; platelet dense granule membrane; autophagosome membrane; azurophil granule membrane; ficolin-1-rich granule membrane; lysosomal lumen; membrane microdomain; endosome; phagocytic vesicle membrane
Gene-disease validity (ClinGen):
ClinGen rates the evidence that LAMP2 causes each of these diseases.
Danon disease (X-linked): Definitive. A lysosomal glycogen storage disease characterized by severe cardiomyopathy and variable degrees of muscle weakness, frequently associated with intellectual deficit.
Homologues: Orthologues: chimpanzee LAMP2 (93% identical), macaque LAMP2 (91% identical), pig LAMP2 (76% identical), rabbit LAMP2 (74% identical), guinea pig LAMP2 (70% identical), dog LAMP2 (70% identical), rat Lamp2 (62% identical), mouse Lamp2 (60% identical), zebrafish lamp2 (25% identical). Paralogues in human: LAMP1 (34% identical), CD68 (18% identical), LAMP5 (11% identical).
Diseases named in the same sentence as LAMP2 in open-access papers:
LAMP2 is named in the same sentence as 243 diseases in open-access papers, as found by Europe PMC text mining. Sharing a sentence is not in itself a finding about the gene and the disease. The quoted sentences say what the papers report.
Danon disease (145 papers, 2005 to 2026). "Danon disease is a rare disorder caused by mutations in the LAMP2 gene, which encodes a lysosomal membrane protein key to the endolysosomal pathway and autophagy." (PMID 42039380, 2026). "Danon disease (DD) is an X-linked lysosomal storage disorder caused by LAMP2 variants, with males presenting more severe phenotypes." (PMID 41560058, 2026). "LAMP2 is associated with Danon disease in humans, which is a dominant X‐linked disorder clinically characterized by hypertrophic cardiomyopathy, skeletal myopathy, and intellectual disability." (PMID 40944391, 2026). "Danon disease (DD) is a rare X-linked disorder caused by pathogenic or likely pathogenic variants in the lysosome-associated membrane protein 2 (LAMP2) gene." (PMID 42154863, 2026). "This study presents 2 detailed cases of male patients diagnosed with Danon disease (DD), a rare X-linked lysosomal storage disorder driven by LAMP2 mutations." (PMID 41560058, 2026). "BACKGROUND: Danon disease (DD) is a rare X-linked cardioskeletal myopathy caused by pathogenic mutations in lysosomal-associated membrane protein-2 (LAMP2)." (PMID 41121270, 2025). "Specifically, the dysfunction of a transmembrane protein, namely the lysosome-associated membrane protein 2 (LAMP-2), has been implicated in the development of cardiac accessory pathways, as seen in Danon disease." (PMID 40308332, 2025). "This approach has also been successful in LAMP2 (lysosomal-associated membrane protein 2) replacement therapy for Danon disease." (PMID 39499917, 2025). "LAMP2, whose deficiency is associated with Danon disease, has three isoforms (LAMP2A, LAMP2B, and LAMP2C), of which one, LAMP2C, has been identified as an RDA receptor." (PMID 39420677, 2025). "Danon disease (glycogen storage disease Type IIB) with LAMP2 deficiency produces severe hypertrophic or dilated phenotypes with lysosomal dysfunction." (PMID 41154572, 2025). "LAMP2 is the gene defective in Danon disease, an X-linked lysosomal storage disorder characterized by severe cardiomyopathy, vacuolar myopathy and intellectual deficit." (PMID 41583011, 2025). "LAMP2 knockout (KO) mice generated by a German group demonstrated that LAMP-2 deficiency causes Danon disease." (PMID 39456205, 2024). "Danon disease (DD) is a lysosomal storage disorder caused by the mutation of the Lysosomal Associated Membrane Protein 2 (LAMP-2) gene." (PMID 38734655, 2024). "Danon disease, an X-linked dominant vacuolar cardiomyopathy and skeletal myopathy, is caused by a primary deficiency of lysosome-associated membrane protein-2 (LAMP-2)." (PMID 39456205, 2024). "For instance, we identified 2 patients below the age of 30, with rare HCM phenocopies: Danon disease and Fabry disease due to pathogenic variants in the LAMP2 (HGNC:6501, NM_002294.3) gene and GLA (HGNC:4296, NM_000169.2) gene, respectively." (PMID 39669619, 2024). "X-linked forms include Anderson–Fabry disease (GLA gene) and Danon disease (LAMP2 gene), while mitochondrial or recessive inheritance, such as in the ALPK3 gene, is often linked to syndromic or pediatric cases." (PMID 39685624, 2024). "Instead, mutations in the lysosome-associated membrane protein 2 (LAMP-2) gene cause Danon disease, which is typically fatal by young adulthood." (PMID 38256355, 2024). "Lamp2-deficient mice model the symptoms of Danon disease in humans, an LSD caused by Lamp2 mutations characterized by abnormal accumulation of AVs in heart and in skeletal muscle." (PMID 39237893, 2024). "According to the results of DNA diagnostics, a diagnosis of Danon’s disease was confirmed: the same pathogenic mutation in a heterozygous state was detected in the LAMP2 gene as in her son." (PMID 39202422, 2024). "Danon disease it is characterized by a deficiency in LAMP2 (lysosomal-associated membrane protein 2)." (PMID 38248465, 2024).
Danon disease (continued). "Mutations in LAMP2 cause Danon disease, an X-linked dominant disorder characterized by hypertrophic cardiomyopathy, skeletal myopathy and mental retardation in males, and a milder, primarily cardiac phenotype in females." (PMID 39501809, 2024). "Human mutations in the X‐linked LAMP2 gene can cause Danon disease (DD), a lysosomal glycogen storage disease with fatal cardiomyopathy." (PMID 39465141, 2024). "Examples of X-linked disorders include Danon disease, caused by pathogenic variants in the LAMP2 gene (GSD type IIB), and Anderson–Fabry disease, a sphingolipidosis caused by pathogenic variants in the α-galactosidase A gene (GLA)." (PMID 38984491, 2024). "Background and Objectives: Danon disease is a multisystemic disorder associated with variants in the LAMP2 gene, mainly affecting the cardiac muscle." (PMID 38256360, 2024). "Most LAMP2 mutations associated with Danon disease cause a loss of function or expression of all LAMP2 isoforms, although some only affect LAMP2B, suggesting that this isoform is central to disease pathogenesis." (PMID 39501809, 2024). "Deficiency of lysosomal membrane proteins has been shown to cause clinical manifestations ranging from severe visceral symptoms to neurodegeneration, and a classic example associated with null mutation of LAMP2 is Danon disease." (PMID 36741911, 2023). "According to Matthew RG Taylor's opinion the diagnosis of Danon disease is established in a proband with suggestive findings and a heterozygous pathogenic variant in LAMP2 identified by molecular genetic testing." (PMID 37288668, 2023). "The diagnosis of Danon disease is based on the identification of LAMP2 gene mutations by NGS sequencing and special suggestive findings." (PMID 37288668, 2023). "Danon disease is an X-linked dominant skeletal and cardiac muscle disorder that is caused by loss-of-function mutations in the LAMP2 gene." (PMID 37762105, 2023). "Danon disease is a rare X-chromosome-associated disorder that is caused by mutations in the gene encoding lysosomal membrane protein 2 (LAMP2)." (PMID 37686045, 2023). "Danon disease is caused by loss-of-function mutations in the lysosome-associated membrane protein 2 (LAMP2) gene, which leads to impaired autophagic degradation and development of cardiomyopathy." (PMID 37596294, 2023). "A loss-of-function mutation in LAMP2 is known to underlie Danon disease which is associated with a defect in autophagic-lysosomal-mediated degradation." (PMID 37596294, 2023). "Loss of function variants in LAMP2 cause Danon disease, a glycogen storage disease also known as X-linked vacuolar cardiomyopathy and myopathy." (PMID 37359372, 2023). "There are only a few reports of Xq24 microdeletions encompassing the LAMP2 gene being the causative factor of Danon disease." (PMID 37628591, 2023). "The underlying pathogenesis of Danon disease is the accumulation of lysosomal material secondary to LAMP2 gene variants that disrupt LAMP2 protein proper function and autophagosome–lysosome fusion in autophagy." (PMID 37628591, 2023). "Identifying and functional analysis of LAMP2 mutations in female Danon disease can broaden our understanding of this rare disease." (PMID 37288668, 2023). "Another model of iPSC-CMs defective in autophagy was produced from two Danon disease patients with different mutations in lysosomal-associated membrane protein type 2 (LAMP-2)." (PMID 37349842, 2023). "Mutations in the LAMP2 gene can lead to Danon disease, an X-linked dominant disease in which patients have weakened bones and heart muscle, leading to multi-organ disease, severe heart failure, and ultimately death." (PMID 37111358, 2023). "In man, genetic mutations in LAMP2 are associated with Danon Disease, a fatal X-linked syndrome caused by lysosomal dysfunction." (PMID 35535798, 2023).
Danon disease (continued). "Danon disease: this is a rare X-linked dominant genetic disorder caused by a deficiency in lysosome-associated membrane protein-2 (LAMP2), leading to lysosomal storage." (PMID 37685777, 2023). "Danon disease is characterized by the failure of lysosomal biogenesis, maturation, and function due to a deficiency of lysosomal membrane structural protein (LAMP2)." (PMID 37288668, 2023). "Danon disease (DD) (OMIM#300257) is a rare X-linked dominant lysosomal glycogen storage disorder induced by lysosome-associated membrane protein-2 (LAMP-2) deficiency." (PMID 37215540, 2023). "Heterozygous mutations causing defects or null function in the protein of LAMP2 were the genetic basis of Danon disease, haploinsufficiency, and X chromosome inactivation skewing determine the severity of the patient's phenotype." (PMID 37288668, 2023). "One study investigated Danon disease, a multisystem disorder with skeletal and cardiac muscle involvement, caused by a mutation in the lysosomal associated membrane protein-2 (LAMP2) gene." (PMID 35870954, 2022). "This glycoprotein provides selectins with carbohydrate ligands, and mutations of LAMP2 cause the classic triad of myopathy, cardiomyopathy and encephalopathy of Danon disease (DD)." (PMID 36313751, 2022). "Introducing the healthy copy of LAMP-2B, the most abundant cardiac isoform of LAMP-2 which is deficient in Danon disease, only partially restored maximal respiratory capacity in diseased iPSC-CMs." (PMID 35870954, 2022). "Danon disease, also called glycogen storage disease type 2B, is a rare lysosomal storage disorder that is caused by mutations in the Lamp2 gene." (PMID 35210514, 2022). "Of particular interest is the Xq24 chromosomal region harboring LAMP2, whose mutations cause Danon disease." (PMID 36009380, 2022). "Danon disease (DD) is caused by mutations of the gene encoding lysosomal-associated membrane protein type 2 (LAMP2), which lead to impaired autophagy, glycogen accumulation, and cardiac hypertrophy." (PMID 36671453, 2022). "Danon disease (DD) is a rare X-chromosome-linked genetic disorder caused by a lysosome-associated membrane protein-2 (LAMP2) gene mutation." (PMID 35299984, 2022). "Danon disease is an X-linked multisystemic disorder caused by a defect in the lysosome-associated membrane protein 2 (LAMP2) gene (Xq24), encoding the LAMP2 protein, leading to progressive accumulation of autophagic material." (PMID 35145940, 2021). "LAMP2 deficiency is associated with Danon disease, which features cardiomyopathy, myopathy, and mental retardation." (PMID 34357353, 2021). "Danon disease (DD) is a rare glycogen storage lysosomal disorder caused by mutations in the LAMP2 gene." (PMID 34901223, 2021). "Danon disease, which occurs due to loss of function mutations in the Lamp2 gene, causes impaired mitophagy, facilitating mitochondrial damage." (PMID 34394711, 2021). "Using this approach, we created an isogenic pair of iPSCs that were genetically identical, differing only in their expression of the specific LAMP2 allele, and used it to model Danon disease." (PMID 34360897, 2021). "Danon disease is caused by mutations in the gene encoding the Lysosome-associated membrane protein 2 (LAMP2), a membrane glycoprotein known to be related to autophagy." (PMID 33841177, 2021). "Danon disease is a multisystem disorder resulting from mutations in the lysosome-associated membrane protein-2 (LAMP2) gene." (PMID 33925963, 2021). "Defective autophagy, like in the case of LAMP-2 deficiency (Danon disease), is associated with increased stiffness and reduced stress response adaptation potential in fibroblasts." (PMID 34012396, 2021). "Previous studies have discovered that Danon disease is associated with mutations in the LAMP2 gene, which is located on the human X chromosome and encodes a lysosomal membrane protein." (PMID 32012649, 2020).